RGSL1 (regulator of G protein signaling like 1)
Synonyms: RGSL; RGSL2
Tractability: Antibody: UniProt predicts a signal peptide or a membrane-spanning region. PROTAC: ubiquitination databases record sites on it.
Gene: Protein-coding gene on chromosome 1 (182,409,192 to 182,560,599, forward strand). Ensembl gene ENSG00000121446.
Subcellular location: Membrane
Pathways (Reactome):
Signal Transduction: G alpha (i) signalling events; G alpha (q) signalling events; G alpha (z) signalling events
Gene Ontology:
Cellular component: membrane
Genetic constraint (gnomAD): Loss-of-function variants: 82 observed, 112.24 expected, observed/expected ratio (o/e) 0.73, 90% interval 0.61 to 0.88. The upper end of that interval is the gene's LOEUF score, 0.88, which puts it in group 3 of 6, group 1 being the genes least tolerant of losing a copy. Missense variants: 1,126 observed, 1,237.6 expected, observed/expected ratio (o/e) 0.91, 90% interval 0.87 to 0.96. Synonymous variants: 399 observed, 430.38 expected, observed/expected ratio (o/e) 0.93, 90% interval 0.85 to 1.01.
Homologues: Orthologues: chimpanzee RGSL1 (99% identical), macaque RGSL1 (91% identical), dog RGSL1 (76% identical), pig RGSL1 (75% identical), mouse Rgsl1 (68% identical), rat Rgsl1 (67% identical), guinea pig RGSL1 (63% identical). Paralogues in human: RGS12 (9% identical), RGS9 (9% identical), RGS6 (9% identical), RGS7 (9% identical), RGS3 (8% identical), RGS22 (8% identical), AXIN1 (7% identical), RGS11 (7% identical), AXIN2 (7% identical), RGS14 (7% identical), RGS5 (5% identical), RGS2 (5% identical), and 11 more.
Diseases named in the same sentence as RGSL1 in open-access papers:
RGSL1 is named in the same sentence as 2 diseases in open-access papers, as found by Europe PMC text mining. Sharing a sentence is not in itself a finding about the gene and the disease. The quoted sentences say what the papers report.
cancer (1 paper, 2021). A tumor composed of atypical neoplastic, often pleomorphic cells that invade other tissues. "In addition, the nine mRNAs of the ceRNA regulatory networks included GRK4, PCYT2 and RGSL1, which showed prognostic relevance and was associated with cancer-related pathways such as DNA Damage, AR, ER, RASMAPK, and TSC-mTOR." (PMID 34621245, 2021). "Finally, the involvement of GRK4, PCYT2 and RGSL1 in cancer-related pathways and drug susceptibility needs further experimental validation." (PMID 34621245, 2021). "Finally, we analyzed the correlation between drug sensitivity of cancer cell lines in GDSC (Genomics of Drug Sensitivity in Cancer), and the GRK4, PCYT2 and RGSL1 expression levels." (PMID 34621245, 2021).
RGSL1 also shares sentences with these, for which no sentence is quoted: breast carcinoma (1 paper).